APOC3 (apolipoprotein C3)
Diseases named in the same sentence as APOC3 in open-access papers (continued):
Sharing a sentence is not in itself a finding about the gene and the disease.
type 2 diabetes (continued). "It was also reported that variants in APOC3 promoters increased type 2 diabetes risk only in lean populations, not in overweight individuals." (PMID 30380775, 2018). "It has been reported that APOC3 is involved in type 2 diabetes." (PMID 27351175, 2016). "A case–control study involving 374 Chinese type 2 diabetic patients with and 392 without diabetic nephropathy found that the hepatic lipase -514C/T polymorphism interaction with polymorphisms in APOC3 -482C/>T increased the risk of diabetic nephropathy." (PMID 25380998, 2014). "To test the mechanistic role of APOC3 and TRLs on DKD, we turned to a mouse model of type 2 diabetes and kidney disease." (PMID 38743496, 2024). "In patients with type 2 diabetes, the elevated serum triglyceride levels negatively correlate with circulating LPL levels, and positively with circulating APOC1, APOC3, ANGPTL3, ANGPTL4 and ANGPTL8 levels." (PMID 37448184, 2023). "Both APOC1 and APOC3 inhibit LPL activation, and the circulation levels are investigated in patients with type 2 diabetes." (PMID 37448184, 2023). "In type 2 diabetes patients with or without diabetic retinopathy, multivariate logistic regression analysis showed that APOC2/APOC3 and APOB/non‐HDL cholesterol, as well as APOE/APOC2, were independently related to the risk for the occurrence and severity of diabetic retinopathy." (PMID 37448184, 2023).
hyperlipidemia (39 papers, 2011 to 2025). "The overexpression of ApoC3 causes hyperlipidemia and promotes atherosclerotic lesion development in mouse models." (PMID 35453604, 2022). "APOC3 deficiency alleviated cholesterol-induced hyperlipidemia and reduced atherosclerotic plaque formation." (PMID 34922545, 2021). "APOC3 is an important molecule in lipid metabolism that is closely associated with hyperlipidemia and an increased risk of developing CVD." (PMID 27619170, 2016). "It has also been reported that APOC3 concentrations are associated with CVDs, including hyperlipidaemia, CHD, and non-alcoholic fatty liver disease." (PMID 27619170, 2016). "GWAS have demonstrated that common mutations within the APOC3 gene are associated with higher TG and many other diseases related to hyperlipidemia." (PMID 27690381, 2016). "Of note is the human leukocyte antigen subtype B*57:01; a strong predictor of abacavir hypersensitivity reactions, as well as variants of the Apolipoprotein C3 (APOC3) promoter region such as C-482T and T-455C associated with development of hyperlipidemia." (PMID 24972136, 2014). "The most significant association was detected for the 3’ UTR of APOC3 (apolipoprotein C3 c.*40G>C) and blood triglyceride levels (p =3.5×10−74 as determined by linear regression), total cholesterol (p =7.6×10−12) and self-reported hyperlipidemia (p = 0.00038)." (PMID 39964837, 2025). "This elevation of ApoC3 levels contributes to hyperlipidemia and hepatic steatosis, potentially exacerbating the aging process." (PMID 38441531, 2024). "Our conclusions indicate that the upregulation of ApoC3 by FoxO6 promotes the development of hyperlipidemia, hyperglycemia, and hepatic steatosis in vivo, and in vitro." (PMID 38441531, 2024). "Taken together, our findings underscore the significance of FoxO6 in driving hyperlipidemia and hepatic steatosis specifically under hyperglycemic states by enhancing the expression of ApoC3 in aged rats." (PMID 38441531, 2024). "In conclusion, the upregulation of ApoC3 via FoxO6 activation leads to the induction of hyperlipidemia and hepatic steatosis in aged rats subjected to an HFD." (PMID 38441531, 2024). "FoxO6, an identified factor, induces hyperlipidemia and hepatic steatosis during aging by activating hepatic lipoprotein secretion and lipogenesis leading to increased ApoC3 concentrations in the bloodstream." (PMID 38441531, 2024). "The limitations of this study were the usage of only three APOC3 KO rabbits without a consistent genotype, suggesting that further in vivo studies are required to elucidate the impact of APOC3 knockout on hyperlipidemia." (PMID 37887310, 2023). "With previous studies suggested that APOC3 was closely with the development of hyperlipidemia and CVD." (PMID 27619170, 2016). "ApoC3 overexpression leads to progressive atherogenesis and post-surgery artery restenosis by accelerating SMC proliferation, and hyperlipidemia could be an additional factor." (PMID 34805315, 2021). "When stratifying by hyperlipidemia, CAD patients with hyperlipidemia had a significantly higher frequency of APOC3 3238 GG genotype (OR =1.73, 95% CI =1.13, 2.64; P = 0.01) than without hyperlipidemia." (PMID 25380998, 2014).
hyperlipidemia (continued). "Although there are numerous studies dealing with ApoC3’s kinetics in HDL and VLDL, ApoC3’s redistribution in postprandial lipemia has not been statistically analyzed so far." (PMID 40562102, 2025).
Hepatic steatosis (25 papers, 2011 to 2026). Steatosis is a term used to denote lipid accumulation within hepatocytes. "The transcriptional activation of FoxO6 induced by both the HFD and high glucose levels resulted in hepatic steatosis by upregulating ApoC3 and genes associated with gluconeogenesis in aged rats and liver cell cultures." (PMID 38441531, 2024). "It is possible that dietary fat has more effect on liver steatosis than carbohydrate-derived fat in humans with the TT genotype of the APOC3 T-455C polymorphism (rs2854116)." (PMID 37304843, 2023). "Carriers of APOA5, GPIHBP1, or LMF1 variants exhibited intermediate TG levels (1800–2500 mg/dL) and substantial pancreatitis risk, whereas APOB and APOC3 variant carriers had milder TG elevations (500–1500 mg/dL) but were more frequently associated with hepatic steatosis and metabolic comorbidities." (PMID 41300829, 2025). "This discovery unveils a potential novel molecular target for therapeutic strategies against hepatic steatosis during the aging process, offering insights into its molecular and cellular underpinnings, particularly its association with FoxO6-mediated ApoC3 upregulation." (PMID 38441531, 2024). "Transgenic mice overexpressing human APOC3 were predisposed to hepatic steatosis, indicating that APOC3 might play an important role in the development of NAFLD 40,41." (PMID 34394242, 2020). "In this context, our investigation aimed to examine the relationship between age-related hepatic steatosis and hyperglycemia, alongside studying how FoxO6 regulates ApoC3 during hyperglycemic conditions in both liver tissues and cells." (PMID 38441531, 2024). "It was found that a variety of gene sites are related to the risk, disease severity, hepatic steatosis and advanced fibrosis of NAFLD, including PNPLA3, TM6SF2, GCKR, MBOAT7, APOC3, HSD17B13, etc.." (PMID 36973654, 2023). "Lipoproteins are composed of lipids, cholesterol and apolipoproteins, and the expression of apolipoproteins A1, A4 and C3 (APOA1, APOA4 and APOC3) increased significantly in the hepatic steatosis groups, suggesting an increased level of cholesterol transport." (PMID 37568219, 2023). "Pairing APOC3 or ANGPTL3 inhibitors with metabolic agents such as GLP-1/GIP receptor agonists may simultaneously address triglyceride burden, hepatic steatosis, pancreatitis risk, and cardiometabolic outcomes." (PMID 41300829, 2025). "Our findings indicate that FoxO6 triggered ApoC3-driven lipid accumulation in the livers of aged rats on an HFD and in FoxO6-Tg, consequently leading to hepatic steatosis and hyperglycemia." (PMID 38441531, 2024). "This review explores current and emerging TG-lowering therapies, including fibrates, omega-3 fatty acids, pemafibrate, and novel agents such as pegozafermin (an FGF21 analog), and APOC3 and angiopoietin-like protein 3 (ANGPTL3) inhibitors, in the context of hepatic steatosis and MASLD." (PMID 42206171, 2026).
familial chylomicronemia syndrome (22 papers, 2016 to 2025). A rare autosomal recessive disease characterized by the buildup in the blood of fat particles called chylomicrons (chylomicronemia), severe hypertriglyceridemia, and the risk of recurrent and potentially fatal pancreatitis and other complications. "Volanesorsen inhibits APOC3 and was approved in Europe for the treatment of familial chylomicronemia syndrome, (Endocrinologic & Metabolic Drugs Advisory Committee, 2018." (PMID 38455763, 2024). "Another ASO, Volanesorsen, which targets apolipoprotein CIII (apoC3), has been used to treat familial chylomicronemia syndrome." (PMID 39125589, 2024). "Volanesorsen, an antisense oligonucleotide targeting APOC3, has proven effective in lowering triglyceride levels in patients with familial chylomicronemia syndrome." (PMID 39286687, 2024). "The ASO targeting APOC3, volanesorsen, is approved for use in patients with familial chylomicronemia syndrome (FCS) in Europe." (PMID 37642858, 2023). "Apolipoprotein C3 (APOC-III) is another target currently being evaluated in patients with familial chylomicronemia syndrome." (PMID 30090066, 2018). "Volanesorsen, a type of medication that targets APOC3 mRNA using antisense oligonucleotides, has proven effective in reducing triglyceride levels in individuals with familial chylomicronemia syndrome, a rare genetic condition characterized by extremely high levels of triglycerides." (PMID 39286687, 2024). "Recently, the approach trial using volanesorsen showed thrombocytopenia in patients of familial chylomicronemia syndrome (FCS), who received ASO-mediated inhibition of ApoC3." (PMID 35187136, 2022).
Hypercholesterolemia (20 papers, 2012 to 2025). An increased concentration of cholesterol in the blood. "A recent study showed the association between the APOC3 genotype and hypercholesterolemia in an HIV-1-infected pediatric cohort exposed to ARV therapy." (PMID 30941184, 2019). "In this pediatric cohort, the evidence for the beneficial effects of APOC3 minor variants on the risk of hypercholesterolemia was limited to an early period after initiation of PI treatment boosted with RTV, and was not verifiable six months later." (PMID 22848358, 2012). "In order to evaluate whether the observed association of APOC3 genotype with TC plasma levels had clinical relevance by significantly changing the susceptibility to HAART-associated hypercholesterolemia, we estimated the risk for each haplotype pair." (PMID 22848358, 2012). "Similarly, APOC3 variants also have an association with hypercholesterolemia." (PMID 32489792, 2020). "In this study, our novel findings provide new insight into the application of ApoC3 inhibition for severe refractory hypercholesterolemia and ASCVD." (PMID 35187136, 2022). "For predicting hypercholesterolemia, the values of AUC remained the highest by sdLDL-C (0.726, 95% CI 0.672-0.779, p < 0.001), followed by apoC3 0.674, 95% CI 0.621-0.728, p < 0.001) and PCSK9 (0.609, 95% CI 0.564-0.654, p < 0.001)." (PMID 27713142, 2017). "For predicting combined hypercholesterolemia, the values of AUC by sdLDL-C, apoC3, and PCSK9 were 0.919, 95% CI 0.891-0.946; 0.879, 95% CI 0.848-0.911; and 0.606, 95% CI 0.563-0.648; respectively (all p < 0.001)." (PMID 27713142, 2017). "A co-dominant genetic model was fitted for APOC3 sites −482, −455 and 3238, and in all cases we found lower hypercholesterolemia risk for heterozygous individuals than for patients without the minor allele under a PI-based regimen boosted with RTV." (PMID 22848358, 2012). "In conclusion, we have demonstrated that targeting ApoC3 could reduce TG levels and ameliorate fatty liver only in female FH hamsters with severe refractory hypercholesterolemia after HCHF diet feeding, but paradoxically accelerated diet-induced atherosclerotic development in dependent on gender." (PMID 35187136, 2022).
Hypertension (19 papers, 2008 to 2024). The presence of chronic increased pressure in the systemic arterial system. "In this sense, some classical CV risk factors such as age and the presence of hypertension were significantly and positively related to higher serum levels of ApoC3." (PMID 35584319, 2022). "The association between apoC3 with hypertension onset was tested in Korean adults aged from 40–69 years over a 9.8-year follow-up." (PMID 36551995, 2022). "On the other hand, humans with an APOC3 mutation benefit from a favorable lipoprotein profile, increased insulin sensitivity, lower incidence of hypertension, and protection against cardiovascular diseases." (PMID 30622162, 2019). "The findings showed that the genotype effects of apoC3 on hypertension risk were evident." (PMID 36551995, 2022). "For instance, decreased APOA4, APOC1, and APOC3 expression would result in reduced lipid removal from the vascular wall and inhibition of lipoprotein lipase activity, potentially promoting lipid accumulation, which might be associated with hypertension." (PMID 34929167, 2022). "We tested whether triglyceride-influencing genetic variants at APOC3 (T-455C, C-482T, C1100T, and SstI) are associated with the onset of hypertension (HTN) among Korean adults stratified by lifestyle-related factors in the Ansung–Ansan cohort within the Korean Genome and Epidemiology Study." (PMID 30380775, 2018). "All PE-like groups showed hypertension and proteinuria except ApoC3+NS mice only showed hypertension." (PMID 25302499, 2014). "However, limited information is available on the effects of apoC3 genetic variation in predicting the development of hypertension." (PMID 36551995, 2022). "Furthermore, after L-NA injection, ApoC3+L-NA mice showed PE-like symptoms, including hypertension and proteinuria, while ApoC3+NS mice showed hypertension alone." (PMID 25302499, 2014).
nonalcoholic fatty liver disease (15 papers, 2011 to 2025). "The apolipoprotein C3 (APOC3) polymorphism has been reported to predispose to non-alcoholic fatty liver disease (NAFLD)." (PMID 34394242, 2020). "To provide further insight into the cardiometabolic properties of HDL subspecies defined by the presence or absence of apoC3, we aimed to examine these subspecies with liver fat content and non-alcoholic fatty liver disease (NAFLD)." (PMID 33142714, 2020).
type 1 diabetes (14 papers, 2014 to 2026). "Experiments in mouse models with type 1 diabetes show that the relative insulin deficiency (which occurs in suboptimally controlled diabetes) increases the serum levels of apolipoprotein C3 and is associated with accelerated atherosclerosis." (PMID 34395631, 2021). "In people with type 1 diabetes, plasma APOC3 levels correlate with levels of albuminuria, potentially suggesting a role for APOC3 in diabetic kidney disease (DKD)." (PMID 38743496, 2024). "This first multi-method characterization study of sdLDL in type 1 diabetes highlights the contribution of ApoC3, CETP and HL to sdLDL-C enrichment and suggests that direct assessment of sdLDL may improve cardiovascular risk stratification." (PMID 42022901, 2026). "Furthermore, we, and others, have recently demonstrated that APOC3 levels are also predictors of cardiovascular events in people with type 1 diabetes." (PMID 38743496, 2024). "Recently, a link between APOC3 and DKD was demonstrated in people with type 1 diabetes participating in the FinnDiane study." (PMID 38743496, 2024). "To address this, we turned to a model of type 1 diabetes in which the pancreatic β cells are lost; thus, APOC3 silencing does not improve blood glucose." (PMID 38743496, 2024). "Furthermore, this is supported by the notion that transgenic overexpression of APOC3, which results in elevated levels of TRLs, augments early DKD in a model of type 1 diabetes, partly via elevated renal inflammation." (PMID 38743496, 2024).
pancreatitis (13 papers, 2017 to 2026). Inflammation of the pancreas. "APOC3 gain-of-function variants are associated with elevated TG levels and pancreatitis, whereas loss-of-function variants confer lifelong protection." (PMID 41300829, 2025). "Some reports suggest that lowering plasma levels of apolipoprotein C-III (APOC3) reduces plasma triglycerides and, furthermore, the risk of TG-associated pancreatitis." (PMID 40507369, 2025). "The drug‐target analyses suggest that targeting APOB, APOC3, and LPL are promising strategies to reduce the risk of multiple forms of pancreatitis, a finding that warrants further investigation." (PMID 41403918, 2025). "These analyses collectively establish distinct causal mechanisms through which APOC3, APOB, and LPL contribute to pancreatitis risk." (PMID 41403918, 2025). "A low-fat diet enriched with MCT oil and fibrate therapy was insufficient to prevent recurrent pancreatitis, and the patient was put on volanesorsen—an antisense oligonucleotide against APOC3 mRNA." (PMID 38872171, 2024). "Four proteins (APOA4, APOC3, IGFBP2 and TIMP1) were significantly altered in PC compared with healthy subjects or pancreatitis using Kruskal-Wallis test (P < 0.01)." (PMID 28514751, 2017). "The higher level of TIMP1, the lower the level of APOA4, APOC3 and IGFBP2 in PC, compared with healthy controls or patients with pancreatitis." (PMID 28514751, 2017).
Stroke (12 papers, 2009 to 2024). Sudden impairment of blood flow to a part of the brain due to occlusion or rupture of an artery to the brain. "The genetic variants at or near HMGCR, NPC1L1, and APOC3 were predicted to decrease lacunar stroke incidence in drug-target MR analysis." (PMID 38275377, 2023). "Taken together, these findings suggest that APOC1 and APOC3 can be markers of hemorhagic stroke, but not of the ischemic stroke subtypes." (PMID 31242583, 2019).